ANXA11 (annexin A11)
Description:
Binds specifically to calcyclin in a calcium-dependent manner (By similarity). Required for midbody formation and completion of the terminal phase of cytokinesis.
Synonyms: CAP-50; ANX11; ALS23; CAP50; IBMWMA
Tractability: Antibody: its Gene Ontology location is reachable by antibodies, with medium confidence. PROTAC: ubiquitination databases record sites on it; its protein half-life has been measured.
Target class: Ion channel; Annexin; Other ion channel
Gene: Protein-coding gene on chromosome 10 (80,150,889 to 80,205,583, reverse strand). Ensembl gene ENSG00000122359.
Subcellular location: Cytoplasm; Melanosome; Nucleus envelope; Nucleus, nucleoplasm; Cytoplasm, cytoskeleton, spindle
Subcellular location (Human Protein Atlas): Nucleoplasm; Cytosol; Vesicles
Gene Ontology:
Molecular function: calcium-dependent protein binding; MHC class II protein complex binding; protein binding; RNA binding; S100 protein binding; calcium-dependent phospholipid binding; phosphatidylserine binding; calcium ion binding; phosphatidylethanolamine binding
Biological process: cytokinetic process; phagocytosis; response to calcium ion
Cellular component: azurophil granule; cytoplasm; cytosol; extracellular exosome; extracellular matrix; membrane; midbody; nuclear envelope; nucleoplasm; phagocytic vesicle; specific granule; spindle; nucleus; plasma membrane; vesicle membrane; melanosome
Genetic constraint (gnomAD): Loss-of-function variants: 48 observed, 56.21 expected, observed/expected ratio (o/e) 0.85, 90% interval 0.68 to 1.09. The upper end of that interval is the gene's LOEUF score, 1.09, which puts it in group 4 of 6, group 1 being the genes least tolerant of losing a copy. Missense variants: 643 observed, 626.07 expected, observed/expected ratio (o/e) 1.03, 90% interval 0.96 to 1.1. Synonymous variants: 248 observed, 243.19 expected, observed/expected ratio (o/e) 1.02, 90% interval 0.92 to 1.13.
Gene-disease validity (ClinGen):
ClinGen rates the evidence that ANXA11 causes each of these diseases.
amyotrophic lateral sclerosis type 23 (autosomal dominant): Definitive.
Homologues: Orthologues: chimpanzee ANXA11 (100% identical), macaque ANXA11 (95% identical), rat Anxa11 (93% identical), mouse Anxa11 (93% identical), rabbit ANXA11 (92% identical), dog ANXA11 (88% identical), guinea pig ANXA11 (86% identical), pig ANXA11 (83% identical), tropical clawed frog anxa11 (72% identical), zebrafish anxa11a (63% identical), zebrafish anxa11b (58% identical), Drosophila melanogaster AnxB11 (36% identical), and 1 more. Paralogues in human: ANXA7 (48% identical), ANXA6 (37% identical), ANXA4 (36% identical), ANXA8 (34% identical), ANXA8L1 (34% identical), ANXA5 (33% identical), ANXA3 (33% identical), ANXA1 (31% identical), ANXA2 (31% identical), ANXA13 (30% identical), ANXA10 (27% identical), ANXA9 (24% identical).
Diseases named in the same sentence as ANXA11 in open-access papers:
ANXA11 is named in the same sentence as 68 diseases in open-access papers, as found by Europe PMC text mining. Sharing a sentence is not in itself a finding about the gene and the disease. The quoted sentences say what the papers report.
sarcoidosis (42 papers, 2012 to 2025). Sarcoidosis is a multisystemic disorder of unknown cause characterized by the formation of immune granulomas in involved organs. "Mutations in ANXA11 are correlated with NS diseases and high risk of inflammatory conditions like sarcoidosis." (PMID 40260118, 2025). "Other genes, including Butyrophilin-like-2 (which influences T-cell regulation), SLC11A1 (which encodes macrophage membrane protein) and Annexin A11 (which is involved in cell apoptosis), are all associated with different sarcoidosis phenotypes." (PMID 40002701, 2025). "Sarcoidosis associated pulmonary fibrosis has some unique features such as variants of annexin A11 and PVT1." (PMID 39281278, 2024). "In a small study involving African - American patients with sarcoidosis, certain ANXA11 single nucleotide polymorphisms (SNPs), namely rs1049550 and rs12779955, were associated with an increased susceptibility to pulmonary fibrosis." (PMID 39281278, 2024). "The number of diseases associated with variants in ANXA11 has broadened substantially since 2006, when a genome‐wide association study first implicated it as a risk gene for autoimmune disease and sarcoid." (PMID 38923692, 2024). "Among the regulators of calcium ion metabolism, the most important gene that is a risk factor for the development of sarcoidosis is ANXA11." (PMID 39598118, 2024). "Recent GWAS in European, African American, and Asian populations identified a non-synonymous single-nucleotide polymorphism (SNP), rs1049550, within the annexin A11 (ANXA11) gene as being associated with susceptibility to sarcoidosis." (PMID 37234239, 2023). "ANXA11 has been strongly linked to sarcoidosis in humans, an inflammatory disease in epithelial tissue." (PMID 36342464, 2022). "Presence of the T allele of rs1049550 in ANXA11 is protective for sarcoidosis, including benign and chronic phenotypes of the disease." (PMID 35563867, 2022). "There is one important aspect to take into account; the minor T allele, which would affect the Annexin A11 function, is actually less frequent in sarcoidosis and therefore its presence protects against sarcoidosis." (PMID 35563867, 2022). "The aim of this study was therefore, first, to investigate the association of the ANXA11 SNP rs1049550 with sarcoidosis in general and corroborate previous findings by adding new results in a meta-analysis." (PMID 35563867, 2022). "In the present study, we investigated if ANXA11 rs1049550 associates with sarcoidosis and with disease phenotypes." (PMID 35563867, 2022). "Several studies have replicated these results and showed an association with the ANXA11 Single Nucleotide Polymorphism (SNP) rs1049550 and sarcoidosis." (PMID 35563867, 2022). "For meta-analysis, we included six previous studies describing the association between ANXA11 rs1049550 and sarcoidosis and the current findings." (PMID 35563867, 2022). "Mutation in annexin A11 has been associated with susceptibility to sarcoidosis and pulmonary fibrosis in sarcoidosis." (PMID 33539409, 2021). "A non-coding SNP (rs61860052) of Annexin A11 has been associated with an increased risk of sarcoidosis-associated uveitis and other variants with pulmonary fibrosis in African American patients." (PMID 32823753, 2020). "Of note, the autoAb against annexin A11 (ANXA11), which is a known susceptibility gene for sarcoidosis, was highly enriched in patients’ sera." (PMID 32046322, 2020). "ANXA11, a sarcoidosis-susceptibility gene, is one of the target antigens of natural autoAbs of sarcoidosis." (PMID 32046322, 2020). "Genome-wide association studies (GWASs) in populations of European descent and/or African-Americans have reported several genetic loci/genes that confer susceptibility to sarcoidosis, including C10orf67, ANXA11, RAB23, OS9, CCDC88B, NOTCH4, and XAF18,9." (PMID 32826979, 2020). "Recent studies show the significant role of annexin A11 in the genetic susceptibility to sarcoidosis." (PMID 27071553, 2016).
sarcoidosis (continued). "Genetic instability and mutation in annexin A11 has been identified in single nucleotide polymorphisms in patients with sarcoidosis compared to control groups." (PMID 27071553, 2016). "A 2014 study of the Han Chinese population confirmed the potential role of ANXA11 SNPs in the genetic susceptibility to sarcoidosis." (PMID 27071553, 2016). "A GWAS conducted using 499 German individuals with sarcoidosis and 490 controls, detected an association to the ANXA11 (annexin 11) gene on chromosome 10q22.3." (PMID 23745122, 2013). "A non-synonymous SNP within ANXA11, rs1049550, was associated with sarcoidosis in our combined AA datasets at PAA-meta = 8.46×10−4." (PMID 22952805, 2012). "Additionally, polymorphisms in the ANXA11 gene are associated with varying risk of developing sarcoidosis, as well as with the chronicity of the disease." (PMID 40002701, 2025). "Thus, with the association of ANXA11 with sarcoid, a systemic autoimmune condition, our multiomic findings suggest that microglial ANXA11 contributes to disease and immune dysregulation, reflecting the importance of disease‐relevant cellular models." (PMID 38923692, 2024). "This locus is nearby the ANXA11 gene, a well-documented locus associated with sarcoidosis." (PMID 36824606, 2023). "Therefore, we can conclude that the association of ANXA11 rs1049550 applies for sarcoidosis in general and the clinical phenotypes of LS and chronic disease." (PMID 35563867, 2022). "However, ANXA11 gene polymorphism rs1049550 is exclusively associated with sarcoidosis, making it a key gene of interest for sarcoidosis disease pathogenesis." (PMID 35563867, 2022). "Now that we established that ANXA11 rs1049550 associates with sarcoidosis in general, regardless of disease phenotype, more research is needed to elucidate the effects of the gene variant on Annexin A11 function and how this effects granuloma formation and maintenance in sarcoidosis patients." (PMID 35563867, 2022). "In addition to the allelic analysis, the association between ANXA11 rs1049550 and total group of sarcoidosis patients, LS, and chronic sarcoidosis patients was assessed for underlying genetic model." (PMID 35563867, 2022). "Furthermore, the rs1049550T in the ANXA11 allele plays a protective role for sarcoidosis in the Chinese Han nationality." (PMID 36226077, 2022). "However, the Open Targets Genetics database shows imputed results for rs1049550, and finds a strong association with sarcoidosis and differential expression of ANXA11 for the lead variant." (PMID 35563867, 2022). "Two loci (ANXA11 and CCDC88B) that were associated with sarcoidosis in previous GWASs showed a PGC < 0.01 in our Japanese discovery set (lead SNP: ANXA11 rs1049550: PGC = 0.0036, OR = 1.24, 95% CI = 1.07–1.43; CCDC88B rs11231740: PGC = 0.0047, OR = 1.27, 95% CI = 1.07–1.50)." (PMID 32826979, 2020). "Interestingly, HLA-DRA has shown to have SNP–SNP interaction with ANXA11, another sarcoidosis associated gene." (PMID 28469621, 2017). "Patients with ANXA11 R230C cannot clear granulomas due to altered apoptosis and may have a higher risk of onset of sarcoidosis and poorer outcome." (PMID 27071553, 2016). "Recently, genetic mutation in annexin A11 was linked to increasing susceptibility to sarcoidosis." (PMID 27071553, 2016). "Strong associations have been repeatedly found between genetic polymorphisms of ANXA11 and sarcoidosis, a systemic immune disorder characterized by destructive, noncaseating epithelioid granulomatous lesions (i.e., nodules caused by inflammation that do not lead to cell death)." (PMID 25961286, 2015).
sarcoidosis (continued). "Moreover, they found high levels of autoantibodies against annexin A11 (ANXA11), a known susceptibility gene for sarcoidosis involved in cell division, apoptosis, and neutrophil function and highly expressed in immune cells such as B cells, monocytes, and myeloid cells." (PMID 36148452, 2022). "It has been suggested that the amino-acid change caused by rs1049550 results in a dysfunctional Annexin A11 which can influence cell processes, thereby altering cell trafficking and apoptosis, which in turn can influence granuloma formation and maintenance, respectively, in sarcoidosis patients." (PMID 35563867, 2022). "Genetic mutations in ANXA11 and BTNL2 appear to influence susceptibility and disease progression in sarcoidosis." (PMID 41306810, 2025). "Among 19 protein-sarcoidosis associations, strong genetic colocalization evidence was observed for 8 pairs, including BTN3A3, ANXA11, ITPKA, BTN3A1, G3BP1, IL1RN, IL2RB, and NFKB1." (PMID 40075078, 2025). "Other genes associated with immune regulation of sarcoidosis, including NOTCH4, TNFα, NOD2, and ANXA11, were also detected by GWAS analysis in different races." (PMID 35860586, 2022). "Annexin A11 is encoded by ANXA11 and was the first gene linked to disease susceptibility in sarcoidosis using the genome-wide association studies approach." (PMID 36543347, 2022). "Taken together, these data may suggest that the pathogenic effect of ANXA11 R230C variant might be owing to a defective apoptosis and/or autophagy inside granuloma, thus inducing a persistent inflammatory reaction and a higher risk of onset of sarcoidosis and poorer outcome." (PMID 32823753, 2020). "These recent advances of annexin A11 in the pre-clinical stage show its significant role in the pathogenesis of sarcoidosis." (PMID 27071553, 2016). "More recent studies have confirmed that Annexin A11 and its regulation of apoptosis is a key genetic player in the development of sarcoidosis." (PMID 27071553, 2016). "Annexin A11 is one of the oldest vertebrate annexins that has a crucial role in sarcoidosis pathogenesis." (PMID 27071553, 2016). "We replicated associations for several previously reported sarcoidosis susceptibility risk loci in our AA collection including MHC Class II region genes (HLA-DRA, HLA-DRB5, HLA-DRB1, and HLA-DQA1), BTNL2, RAB23, and ANXA11." (PMID 22952805, 2012). "The first GWAS study of sarcoidosis identified common nonsynonymous SNP (rs1049550) within the annexin 11 (ANXA 11) regulator of cell apopoptosis gene to be strongly associated with the disease." (PMID 23152861, 2012). "Furthermore, LTBR showed significant associations in the sarcoidosis UK Biobank cohort using the significant-variant strategy, while VEGFB and ANXA11 showed associations using the same-variant strategy." (PMID 39824903, 2025). "Indeed, the functional role of ANXA11 in cell division and apoptosis and the regulation of inflammatory cells make ANXA11 an attractive biomarker for sarcoidosis." (PMID 37250650, 2023). "However, sarcoidosis is a heterogeneous disease and contradictory findings for ANXA11 have been reported for disease phenotypes." (PMID 35563867, 2022). "Prior to further experimental studies into the role of ANXA11 in sarcoidosis, it is essential to determine for which phenotypes the T allele may protect." (PMID 35563867, 2022). "ANXA11 is currently the only gene identified by GWAS that predisposes to sarcoidosis but not to other immune mediated diseases." (PMID 35563867, 2022).
sarcoidosis (continued). "Finally, and most convincingly, the R230C variant and several other SNPs in the N- and C-terminal region of Anxa11 have been associated with neurodegenerative and autoimmune disorders, such as ALS and sarcoidosis." (PMID 33810523, 2021). "In a 2013 study, the role of annexin A11 in sarcoidosis was confirmed in a US population." (PMID 27071553, 2016). "Third, we selected only five polymorphisms from TNF-α and TNF-β genes, and did not cover other sarcoidosis-susceptibility genes, such as annexin A11 gene and butyrophilin-like 2 gene." (PMID 24244632, 2013). "Some identified genes that may be associated with increased susceptibility to sarcoidosis are butyrophilin-like 2 gene (BTNL2), annexin A11 (ANXA11), and angiotensin-converting enzyme (ACE) variants; these associations, however, show high variability across populations." (PMID 39274446, 2024). "Genome-wide linkage and some studies have suggested that several genes may be associated with increased susceptibility to sarcoidosis, such as butyrophilin-like 2 gene (BTNL2), annexin A11 (ANXA11), and angiotensin-converting enzyme variants, although the associations vary across populations." (PMID 37108489, 2023). "Similarly, two ANXA11 variants are associated with sarcoidosis in African Americans, but not in European Americans." (PMID 37621457, 2023). "ANXA11 may therefore provide the key to understanding sarcoidosis-specific disease processes." (PMID 35563867, 2022). "However, ANXA11 is also an amyotrophic lateral sclerosis (ALS)-associated gene, although the sites of mutation among patients with ALS are different from those found in sarcoidosis patients." (PMID 32046322, 2020). "Overall, SNPs from the following genes have already been identified in previous studies on sarcoidosis (GWAS or other): CCDC88B, ANXA11, IL23R, FAM117B, CCL24, ATXN2/SH2B3." (PMID 41466414, 2025). "Among those, CCDC88B and ANXA11 are potential regulators of apoptosis, whereas CCL24 was increased in broncho-alveolar lavage (BAL) of patients with stage 3 sarcoidosis compared to patients with Lo ̈ fgren syndrome and IL23R has been implicated in the formation of granulomas." (PMID 41466414, 2025).